SLC9A6 (solute carrier family 9 member A6)
Description:
Endosomal Na(+), K(+)/H(+) antiporter. Mediates the electroneutral exchange of endosomal luminal H(+) for a cytosolic Na(+) or K(+). By facilitating proton efflux, SLC9A6 counteracts the acidity generated by vacuolar (V)-ATPase, thereby limiting luminal acidification. Responsible for alkalizing and maintaining the endosomal pH, and consequently in, e.g., endosome maturation and trafficking of recycling endosomal cargo. Plays a critical role during neurodevelopment by regulating synaptic development and plasticity (By similarity). Implicated in the maintenance of cell polarity in a manner that is dependent on its ability to modulate intravesicular pH. Regulates intracellular pH in some specialized cells, osteoclasts and stereocilia where this transporter localizes to the plasma membrane (By similarity).
Synonyms: NHE-6; KIAA0267; NHE6; MRSA; MRXSCH; NDPACX
Tractability: Antibody: UniProt places it where antibodies can reach, with high confidence; its Gene Ontology location is reachable by antibodies, with high confidence; UniProt predicts a signal peptide or a membrane-spanning region; the Human Protein Atlas places it where antibodies can reach. PROTAC: UniProt records ubiquitination sites on it; ubiquitination databases record sites on it; its protein half-life has been measured.
Gene: Protein-coding gene on chromosome X (135,973,841 to 136,047,269, forward strand). Ensembl gene ENSG00000198689.
Subcellular location: Endosome membrane; Recycling endosome membrane; Early endosome membrane; Late endosome membrane; Cell membrane
Subcellular location (Human Protein Atlas): Vesicles; Plasma membrane
Pathways (Reactome):
Disease: Defective SLC9A6 causes X-linked, syndromic mental retardation,, Christianson type (MRXSCH)
Transport of small molecules: Sodium/Proton exchangers
Gene Ontology:
Molecular function: identical protein binding; protein binding; potassium:proton antiporter activity; sodium:proton antiporter activity; antiporter activity
Biological process: axon extension; dendrite extension; establishment of cell polarity; neuron projection morphogenesis; regulation of intracellular pH; sodium ion import across plasma membrane; sodium ion transmembrane transport; monoatomic cation transport; potassium ion transmembrane transport; proton transmembrane transport; regulation of pH; sodium ion transport; transmembrane transport
Cellular component: early endosome membrane; endoplasmic reticulum membrane; endosome membrane; late endosome membrane; mitochondrion; plasma membrane; recycling endosome; recycling endosome membrane; membrane
Gene-disease validity (ClinGen):
ClinGen rates the evidence that SLC9A6 causes each of these diseases.
Christianson syndrome (X-linked): Definitive. A very rare form of syndromic intellectual deficit characterized by microcephaly, severe developmental delay or regression, hypotonia, abnormal movements, and early-onset seizures.
Homologues: Orthologues: dog SLC9A6 (99% identical), pig SLC9A6 (98% identical), chimpanzee SLC9A6 (95% identical), macaque SLC9A6 (95% identical), rabbit SLC9A6 (95% identical), mouse Slc9a6 (94% identical), rat Slc9a6 (94% identical), tropical clawed frog slc9a6 (83% identical), zebrafish slc9a6a (77% identical), guinea pig SLC9A6 (72% identical), zebrafish slc9a6b (72% identical), Caenorhabditis elegans nhx-2 (19% identical), and 1 more. Paralogues in human: SLC9A7 (70% identical), SLC9A9 (58% identical), SLC9A8 (28% identical), SLC9A3 (25% identical), SLC9A5 (25% identical), SLC9A2 (24% identical), SLC9A4 (23% identical), SLC9A1 (23% identical), SLC9C1 (15% identical), SLC9C2 (14% identical).
Diseases named in the same sentence as SLC9A6 in open-access papers:
SLC9A6 is named in the same sentence as 60 diseases in open-access papers, as found by Europe PMC text mining. Sharing a sentence is not in itself a finding about the gene and the disease. The quoted sentences say what the papers report.
Christianson syndrome (34 papers, 2014 to 2025). "SLC9A6 variants are associated with Christianson Syndrome, a severe neurodevelopmental disorder that is accompanied by seizures." (PMID 40722028, 2025). "Originally described as the genetic cause of Christianson syndrome in hemizygous males, SLC9A6 has now emerged as a critical gene involved in endosomal homeostasis and neuronal resilience throughout the lifespan." (PMID 41357349, 2025). "Christianson syndrome (CS) is an X-linked disorder resulting from loss-of-function (LoF) mutations in SLC9A6 encoding the endosomal Na+/H+ exchanger 6 (NHE6)." (PMID 37747131, 2023). "Christianson syndrome (CS) is caused by mutations in SLC9A6 and is characterized by global developmental delay, epilepsy, hyperkinesis, ataxia, microcephaly, and behavioral disorder." (PMID 37381736, 2023). "Background and Objectives: The pathogenic variants of SLC9A6 are a known cause of a rare, X-linked neurological disorder called Christianson syndrome (CS)." (PMID 35334527, 2022). "Here, we report a Chinese boy presenting with Christianson syndrome due to novel splicing variant NM_001042537.1: c.1463‐1G>A in the SLC9A6 gene." (PMID 34791706, 2022). "We investigated the existence and potential pathogenicity of a SLC9A6 splicing variant in a Chinese boy with Christianson Syndrome (CS), which was reported for the first time in China." (PMID 35095740, 2022). "NHE6/SLC9A6 mutations lead to neurological phenotypes associated with syndromic autism, broadly characterized into overlapping clinical categories: Christianson syndrome, Angelman-like syndrome, corticobasal degeneration with tau deposition, and epilepsy." (PMID 34445065, 2021). "Mutations in SLC9A6 have been associated with Christianson syndrome (OMIM#300243), which is mainly characterized by severe intellectual disability, no speech, postnatal microcephaly, early onset seizures, ataxia, and hyperactivity." (PMID 31906484, 2020). "Christianson syndrome (CS) is an X-linked neurogenetic disorder resulting from loss-of-function (LoF) mutations in SLC9A6, which encodes the endosomal Na+/H+ exchanger 6 (NHE6)." (PMID 31676550, 2019). "Christianson Syndrome, a recently identified X-linked neurodevelopmental disorder, is caused by mutations in the human gene SLC9A6 encoding the recycling endosomal alkali cation/proton exchanger NHE6." (PMID 27590723, 2016). "Editors' choice:Slc9a6 knockout mice are a model of the X-linked neurodevelopmental and neurological disorder, Christianson syndrome." (PMID 26515654, 2016). "In 1999, the variant involved in SLC9A6 was first described to underlie Christianson syndrome, characterized by moderate-to-severe intellectual disability with absent or very limited language development, epilepsy, ataxia, hyperkinetic behavior, and acquired microcephaly." (PMID 33897753, 2021). "A one-year-old boy debuted with focal epilepsy due to a de novo mutation in chromosome Xq26.3, which led to disturbances in SLC9A6 (solute carrier family 9 member A6) associated with Christianson syndrome (intellectual disability, epilepsy, ataxia, and postnatal microcephaly)." (PMID 33806661, 2021). "Thus far, besides V-ATPase, the alkali cation/proton exchanger SLC9A6/NHE6, whose mutations are linked to Christianson syndrome, is known to be implicated in the intraluminal pH homeostasis in endocytic vesicles, namely in recycling endosomes." (PMID 32511278, 2020). "Christianson syndrome is caused by genetic variants in SLC9A6 on the X chromosome." (PMID 32722525, 2020). "A loss of function mutation in SLC9A6 (Xq26.3) is responsible for Christianson syndrome in males." (PMID 30937176, 2019). "SLC9A6 mutations cause Christianson Syndrome, a severe X-linked neurodevelopmental disorder characterized by intellectual disability with non-verbal status, post-natal microcephaly, seizures, truncal ataxia, and hyperkinetic behavior, plus secondary motor regression and cerebellar atrophy." (PMID 31676550, 2019).
Christianson syndrome (continued). "While hemizygous SLC9A6 mutations in males cause Christianson syndrome, a severe neurodevelopmental disorder, emerging evidence indicates that female carriers may develop progressive, adult-onset Parkinsonian syndrome variably accompanied by cognitive decline and psychiatric symptoms." (PMID 41357349, 2025). "Previously, SLC9A6 variants have been reported to be associated with X-linked syndromic intellectual developmental disorder (MRXSCH, OMIM # 300243), as known as Christianson Syndrome (CS)." (PMID 40722028, 2025). "Loss-of-function mutations in the X-linked endosomal Na+/H+ exchanger 6 (NHE6, encoded by the SLC9A6 gene) cause the neurological disorder Christianson syndrome (CS)." (PMID 39002678, 2024). "Other neurobehavioral phenotypes have been described for Slc9a6- mice, which also recapitulate symptoms in Christianson syndrome patients, for example, hyposensitivity to pain." (PMID 34617884, 2021). "Loss-of-function mutations in SLC9A6, encoding Na+/H+ exchanger 6 (NHE6), cause Christianson syndrome." (PMID 31676550, 2019). "Christianson syndrome (CS) is an X-linked disorder resulting from loss-of-function mutations in SLC9A6, which encodes the endosomal Na+/H+ exchanger 6 (NHE6)." (PMID 29349289, 2017). "However, some Slc9a6 mutant variants causing Christianson syndrome in humans do not significantly alter the ion exchange properties of NHE6 suggesting that Christianson syndrome could be caused by loss of NHE6 scaffolding functions and not by loss of endosomal pH regulation." (PMID 34617884, 2021).
epilepsy (21 papers, 2011 to 2025). A brain disorder characterized by episodes of abnormally increased neuronal discharge resulting in transient episodes of sensory or motor neurological dysfunction, or psychic dysfunction. "Variants in SLC9A6 are associated with CS, a syndromic form of X-linked cognitive disability characterized by epilepsy, moderate to severe ID, progressive microcephaly, motor delay, and very limited language development." (PMID 40722028, 2025). "In the present study, five hemizygous SLC9A6 variants were detected in five unrelated males with epilepsy and/or developmental disorders." (PMID 40722028, 2025). "SLC9A6 hemizygous variants, including three null and two missense variants, were identified in five males with epilepsy." (PMID 40722028, 2025). "Variants in the endosomal solute carrier family 9 member A6 (SLC9A6)/(Na+,K+)/H+ exchanger 6 (NHE6) gene have been linked to epilepsy, speech loss, truncal ataxia, hyperkinesia, and postnatal microcephaly." (PMID 34791706, 2022). "We identified a novel splicing mutation (NM_006359.2:c.1141-8C>A) of SLC9A6 in a seven-year-old boy with microcephaly, severe developmental delay, and intractable epilepsy." (PMID 30937176, 2019). "A mutation in the X-linked SLC9A6 gene in males results in intellectual disability, epilepsy, and ataxia, a phenotype similar to Angelman syndrome." (PMID 24304607, 2013). "At present, clinical genetic testing for SLC9A6 mutations is available through multigene panels for epilepsy and neurodevelopmental disorders or next-generation sequencing platforms in many developed countries, but access remains limited in low-resource settings." (PMID 41357349, 2025). "It is unknown whether SLC9A6 variants are associated with pure epilepsies, and the mechanisms underlying phenotypical variations remain elusive." (PMID 40722028, 2025). "The present study showed that SLC9A6 missense variants are potentially associated with mild epilepsy without developmental delay." (PMID 40722028, 2025). "Therefore, the phenotype spectrum of SLC9A6 potentially ranges from mild epilepsy with favorable outcome, to refractory epilepsy with neurodevelopmental disorders, even to early death, which is less often clinically diagnosed." (PMID 40722028, 2025). "Indeed, we report for the first time post-operative seizure outcomes for six genetic causes of epilepsy: COL4A1, GRIN2B, NEXMIF, NSD1, SCN2A and SLC9A6." (PMID 37264783, 2023). "Mutations in endosomal NHE6 (also known as SLC9A6) are associated with intellectual disability, postnatal microcephaly, absent speech, ataxia with progressive cerebellar atrophy, epilepsy, and neurologic regression." (PMID 29349289, 2017). "An additional family of 6 affected males with severe mental retardation, absent speech, autism spectrum disorder, epilepsy, late-onset ataxia, weakness and dystonia with stereotyped hand movements was reported and an in-frame 9 base-pair deletion in SLC9A6 was identified." (PMID 21569638, 2011).
microcephaly (16 papers, 2014 to 2025). A congenital or acquired developmental disorder in which the circumference of the head is smaller than normal for the person's age and sex.
Intellectual disability (14 papers, 2013 to 2024). "The female SLC9A6 mutation carrier phenotypic spectrum encompasses learning difficulties, speech and language delay, mild-to-moderate intellectual disability, and behavioral issues." (PMID 37213903, 2023). "Variants in SLC9A6 are associated with Mental retardation, X-linked syndromic (MRXSCH), Christianson type [MIM 300243]." (PMID 30500859, 2018). "Through state-of-the-art in silico studies, we explored the impact of these mutations, G448R in SLC9A6 and P493L in SLC13A3, on protein stability and function and their potential link to the development of intellectual disability." (PMID 37794328, 2023).
Angelman syndrome (7 papers, 2013 to 2025). A neurogenetic disorder characterized by severe intellectual deficit and distinct facial dysmorphic features. "In hemizygous males, mutations in SLC9A6 lead to the classical MRXSCH phenotype, which partially overlaps with the clinical presentation of Angelman syndrome." (PMID 41357349, 2025). "In clinical populations, point mutations of Slc9a6 that target NHE6 for increased degradation are associated with aberrant glutamate/glutamine recycling in polarized neurons, which is believed to contribute to Angelman syndrome-like X-linked mental retardation." (PMID 23755101, 2014).
autism (7 papers, 2014 to 2022). Persistent deficits in social interaction and communication and interaction as well as a markedly restricted repertoire of activity and interest as well as repetitive patterns of behavior. "SLC9A6, the gene encoding NHE6, is one of six most recurrently mutated loci in patients with XLID and has been linked to autism comorbid with seizures." (PMID 25002837, 2014). "Another report has also demonstrated downregulation of SLC9A6 expression in the autism postmortem brain, indicating that the pathophysiology may be related to a subset of autism." (PMID 25273398, 2014).
developmental delay (5 papers, 2018 to 2025). "The patient was diagnosed with CS based on SLC9A6 mutation and clinical manifestations of developmental delay, intermittent convulsions, and developmental regression for 2 months." (PMID 37213903, 2023).
lysosomal storage disease (5 papers, 2016 to 2025). A metabolic disorder caused by mutations in proteins critical for lysosomal function, including lysosomal enzymes, lysosomal integral membrane proteins, and proteins involved in the post-translational modification and trafficking of lysosomal proteins. "SLC9A6 knockout mouse models revealed abnormalities in endosomal-lysosomal function and cholesterol accumulation in specific neuronal populations, similar to those in primary lysosomal storage diseases." (PMID 37794328, 2023).
Alzheimer disease (4 papers, 2021 to 2024). A progressive, neurodegenerative disease characterized by loss of function and death of nerve cells in several areas of the brain leading to loss of cognitive function such as memory and language. "To investigate if NHE6/Slc9a6 deficiency contributes to APP processing by BACE1 in neurons, we used primary neurons derived from AppSwe (Tg2576) mice, an Alzheimer’s disease (AD) mouse model that overexpresses human APP with the ‘Swedish’ mutation." (PMID 34617884, 2021). "The Slc9a6 is found to be downregulated in both Parkinson’s and Alzheimer’s disease." (PMID 38891920, 2024).
autism spectrum disorder (4 papers, 2021 to 2023). A spectrum of developmental disorders that includes autism, and Asperger syndrome. "Pathogenic mutations in the solute carrier family 9-member A6 gene (SLC9A6), encoding Na+/H+ exchanger protein member 6 (NHE6), have been associated with CS and autism spectrum disorders." (PMID 37213903, 2023). "Pathogenic mutations in the SLC9A6 gene, which encodes the Na+/H+ exchanger protein member 6 (NHE6), are associated with CS and autism spectrum disorder in males." (PMID 34987551, 2021).
Cerebellar atrophy (3 papers, 2017 to 2024). Cerebellar atrophy is defined as a cerebellum with initially normal structures, in a posterior fossa with normal size, which displays enlarged fissures (interfolial spaces) in comparison to the foliae secondary to loss of tissue. "Neuropathological studies have shown that cerebellar atrophy was caused by neuronal loss of Purkinje cells, and extensive progressive loss of Purkinje cells and gelatinization were observed in the cerebellum of SLC9A6 mutant mice." (PMID 37213903, 2023).
Cognitive impairment (3 papers, 2016 to 2025). Abnormal cognition is characterized by deficits in thinking, reasoning, or remembering. "It has been demonstrated that mutations in the SLC9A6 gene can result in a syndrome characterized by mental retardation, tau deposition and neurodevelopmental delay, as well as cognitive impairment." (PMID 39965013, 2025). "The identification of NDPACX, an X-linked neurodegenerative disorder manifesting as Parkinsonian syndrome and cognitive impairment in female carriers of SLC9A6 mutations, challenges the conventional dichotomy between neurodevelopmental and neurodegenerative disease paradigms." (PMID 41357349, 2025). "This pattern of congenital cognitive impairment suggests a developmental origin, likely due to endosomal-lysosomal dysfunction caused by SLC9A6 mutations, rather than tau accumulation." (PMID 41357349, 2025).
Parkinson’s (3 papers, 2014 to 2025). "A study showing novel SLC9A6 gene mutations in Christianson syndrome males noted signs of Parkinsonism in obligate carrier females from the same families, suggesting a predisposition to late-onset neurodegenerative disorders." (PMID 25002837, 2014). "Furthermore, recent findings have linked reduced SLC9A6 expression to the increased vulnerability of the substantia nigra in sporadic Parkinson’s disease, suggesting a broader relevance beyond rare monogenic disorders." (PMID 41357349, 2025).
attention deficit-hyperactivity disorder (2 papers, 2014 to 2022). A disorder characterized by a marked pattern of inattention and/or hyperactivity-impulsivity that is inconsistent with developmental level and clearly interferes with functioning in at least two settings (e.g. at home and at school). "The Na+/H+ exchanger 6 and 9 (NHE6/9 or SLC9A6/9) has been identified as candidate gene of interest for attention deficit hyperactivity disorder (ADHD) and ASD." (PMID 36466804, 2022).
focal epilepsy (2 papers, 2021 to 2025). A seizure caused by a localized disorder. "The results suggested that SLC9A6 variants are potentially associated with partial epilepsy with favorable outcomes." (PMID 40722028, 2025). "Missense variants in SLC9A6 are potentially associated with partial epilepsy with favorable outcomes." (PMID 40722028, 2025). "Missense variants in SLC9A6 are associated with mild partial epilepsies." (PMID 40722028, 2025).